IDH1 (isocitrate dehydrogenase (NADP(+)) 1)
Diseases named in the same sentence as IDH1 in open-access papers (continued):
Sharing a sentence is not in itself a finding about the gene and the disease.
glioma (continued). "More recently, 13C MRS studies have demonstrated a drastic reduction in lactate production by IDH1 mutated gliomas that are unaffected by treatment." (PMID 38137775, 2023). "IDH1 mutations are characteristic of low-grade glioma and secondary glioblastoma, where depending on the type of tumor, 30% to 85% of tumors have this mutation." (PMID 37046844, 2023). "This combination incorporates immune and metabolic factors, not only accurately predicting the prognosis, but also distinguishing different glioma molecular subtypes, including IDH1 mutation, MGMT promoter methylation, and 1p/19q co-deletion." (PMID 37891828, 2023). "Isocitrate dehydrogenase 1 (IDH1) is frequently mutated in human gliomas, especially the R132H mutation of IDH1." (PMID 36969840, 2023). "For example, mutation of a single gene, isocitrate dehydrogenase 1 (IDH1) is a driver of the CpG island methylator phenotype (CIMP) in gliomas." (PMID 37169948, 2023). "A total of 115 glioma patients were included, of which 82 (71.3%) patients expressed IDH1 gene mutation and five (4.35%) patients expressed IDH2 gene mutation." (PMID 37250582, 2023). "Cancers frequently associated with a CIMP-high phenotype include colorectal cancer (CRC) and glioma, with BRAF (CRC) and IDH1 (glioma) mutations also associated with this phenotype, as well as with microsatellite instability in CRC42." (PMID 36928603, 2023). "For example, scRNA-Seq analyses on GBM patient tumors resulted in identification of a subset of high-grade glioma–associated microglia (HGG-AM) in IDH1-WT/SETD2-mutant GBM." (PMID 36594466, 2023). "Based on their molecular profile, a significant proportion of adult-type gliomas can be subtyped by IDH (IDH1 or IDH2) and ATRX mutation status, as well as 1p19q codeletion." (PMID 38106649, 2023). "Meanwhile, it has been confirmed in many studies that IDH1 mutations and loss of 1p or 19q or co-deletion of both are of prognostic significance in glioma patients." (PMID 37697240, 2023). "In their study, Li and colleagues reported that SIRT5 has the ability to counteract metabolic abnormalities and apoptosis resistance in glioma cells harboring IDH1 mutation, resulting in impaired cell growth both in vitro and in vivo." (PMID 37175631, 2023). "As rs11706832 has a specific susceptibility for IDH1-mutated low-grade gliomas, we validated the genes found in the HEK293T cell lines using gene count data from TCGA for 325 IDH1 mutated primary LGGs9." (PMID 37185361, 2023). "Currently, molecular markers for adult glioma classification and prognosis include IDH1/2 mutations, homozygous deletion of CDKN2A and/or CDKN2B, EGFR amplification, and TERT promoter mutation." (PMID 37214395, 2023). "Another study using the RCAS/TVA system demonstrated that glioma-genesis in the context of mutant IDH1 with shp53 and/or Cdkn2a loss, was only facilitated when combined with PDGFa." (PMID 38012788, 2023). "Mutations in IDH1/2 are characteristic for lower-grade gliomas and are associated with a better prognosis." (PMID 37400829, 2023). "Adult gliomas often exhibit genetic alterations such as mutations in the IDH1/2 genes, EGFR amplification, and loss of chromosome 10q." (PMID 37444408, 2023). "As one of the landmark events in progression of glioma, Isocitrate dehydrogenase type 1 (IDH1) mutations have been constantly studied as a potential therapeutic target, among which IDH1(R132H) is the most frequent one." (PMID 37046332, 2023). "IDH1 (Isocitrate dehydrogenase 1) mutations are somatic mutations in gliomas that are associated with a better prognosis." (PMID 37476290, 2023).
glioma (continued). "Preclinical studies evaluated IDH inhibition together with immune checkpoint inhibition (ICI) to enhance efficacy of adoptive T-cell transfer of mice vaccinated with a IDH1-R132H peptide or peptides derived from glioma-associated antigens." (PMID 36566461, 2023). "In this study, we first defined that GALNT2 expression was high in GBM, GSCs, and IDH1 wildtype gliomas, and elevated GALNT2 expression was also associated with unfavorable GBM patients’ clinical outcomes." (PMID 37000153, 2023). "Here the challenge is the frequent overlap of MGMT promoter methylation with the IDH1 mutation, which, in conjunction with relatively small number of patients in the high-grade glioma studies, presents difficulties in statistical analysis." (PMID 37341199, 2023). "Together, these findings suggest that retention of wild-type IDH1 in gliomas enhances clinical success of T cell-activating immunotherapy, whereas IDH1 loss impairs local anti-tumor T cell responses and leads to immunotherapy failure." (PMID 37161052, 2023). "The prognostic implication of IDH1/2 mutations in gliomas, chondrosarcoma, and cholangiocarcinoma have similarly been established." (PMID 36937407, 2023). "It was explicable that intraoperative sampling was inaccurate, or the heterogeneity of glioma, although it has been reported that IDH1 mutations are early, stable molecular events in glioma." (PMID 37029174, 2023). "In our research, up-regulated in IDH1-WT gliomas, TRIM21 was associated with advanced tumor grade and poor prognosis." (PMID 37771771, 2023). "IDH1/2 (isocitrate dehydrogenase 1/2) mutations globally change DNA methylation patterns in gliomas." (PMID 36850002, 2023). "Isocitrate dehydrogenase 1 (IDH1) mutation is commonly shown in about 80% of low-grade gliomas, and patients with IDH1 mutation frequently have a favorable prognosis, thus IDH1 mutational status is a strong prognostic biomarker for gliomas." (PMID 37000153, 2023). "In the new 2021 WHO guidelines, IDH1 mutation is a histopathological characterization of all lower-grade gliomas and, of those, 37–50% carry the 1p/19q co-deletion." (PMID 36831380, 2023). "GALNT2 mRNA expression was abnormally increased in IDH1 wild-type gliomas compared with the mutated gliomas." (PMID 37000153, 2023). "The presence of the IDH1 R132H mutation in glioma is associated with better clinical outcomes through enhancing sensitivity to temozolomide via regulation of the ATM/CHK2 pathway." (PMID 36835465, 2023). "Specifically, IDH1 gene mutation in the codon 132 is a frequent mutation present in low-grade gliomas (around 80%) and secondary glioblastomas." (PMID 36986469, 2023). "Another study, aimed to assess the effectiveness of radiomics in categorizing patients with low-grade gliomas based on their IDH1 mutations and 1p/19q codeletion status." (PMID 37568660, 2023). "IDH1-mutant glioma lines are more susceptible to oleic acid-induced apoptosis than wildtype counterparts." (PMID 37108511, 2023). "Lower-grade gliomas, for example, are characterized by the presence of the mutated enzyme isocitrate-dehydrogenase-1 (IDH-1)." (PMID 36901897, 2023). "Lower-grade gliomas, which most commonly have the isocitrate dehydrogenase 1 (IDH1) mutation, were investigated using hyperpolarized [1-13C] pyruvate MRSI and presented with a lower pyruvate-to-lactate conversion compared to GBM models." (PMID 37233647, 2023). "IDH2, which is an analog of IDH1, is predominantly localized in mitochondria but mutated in gliomas at much lower frequencies." (PMID 37108511, 2023).
glioma (continued). "Randomised clinical trials in patients with glioma receiving radiotherapy showed that only patients having IDH1 mutated tumours benefited significantly from radiotherapy combined with adjuvant chemotherapy." (PMID 37273917, 2023). "We examined the impact of mutated and wild-type IDH1 on host survival after vaccine immunotherapy, in both glioma-bearing mice and GBM patients." (PMID 37161052, 2023). "Contrastingly, in glioma and leukemia, IDH1 mutations that result in 2-hydroxyglutarate production disrupts TET2 function and establishes CIMP and global DNA hypermethylation." (PMID 37234978, 2023). "Another factor to consider is D-2-hydroxyglutamate, which is released by glioma cells with an IDH1 mutation." (PMID 38067243, 2023). "Since the discovery of IDH1 mutation in gliomas, IDH1 mutation has been considered one of the most fundamental genetic alterations in diffuse lower-grade gliomas (LGGs)." (PMID 38012788, 2023). "Although the IDH1 mutation is common in low-grade glioma, in primary glioblastoma, less than 10% of tumors have the IDH1 mutation." (PMID 37046844, 2023). "The IDH1 mutation status and chr1p19q co-deletion status are key genomic markers related to the prognosis of glioma treatment." (PMID 37955724, 2023). "Some relevant studies were based on sketching the overall glioma region when constructing radiomic models to predict IDH1 gene mutations." (PMID 37354775, 2023). "Such inhibition is relevant to IDH1-mutated gliomas, which are typically low-grade tumors and rarely seen among GBM." (PMID 37161052, 2023). "IDH1 mutation is one of the most important molecular features of glioma and is significantly related to the prognosis of patients." (PMID 37952042, 2023). "Early studies specified that nanomechanical properties of gliomas depend on the IDH1 R132H mutation." (PMID 36835465, 2023). "TMIGD2 expression was found to be significantly higher in astrocytoma, IDH-1 mutations, low-grade, and young glioma patients." (PMID 37261362, 2023). "Although mutations of either IDH1 or IDH2 in gliomas are heterozygous, they have an impact on drug resistance as both IDH1 and IDH2 form homodimers to exert their catalytic function and mutant homodimers and heterodimers are inactive." (PMID 38068493, 2023). "Gliomas with IDH1/2 mutations display a distinct methylation pattern characterized by DNA hypermethylation of CpG islands, the so called CpG island methylator phenotype (CIMP)." (PMID 36739454, 2023). "Here, we discover that IDH1 mutation inhibits virus-induced interferon (IFN) antiviral responses in glioma cells." (PMID 37880243, 2023). "Cartilage tumours and cholangiocarcinoma mainly have IDH1 p.R132C variants (~60%), glioma predominantly harbours IDH1 p.R132H mutations (~90%), and AML often has IDH2 p.R140Q mutations (~40%)." (PMID 37509266, 2023). "Previous studies have reported that IDH1 mutations associated with younger age had increased overall survival in patients diagnosed with glioma." (PMID 37621817, 2023). "Mutation at Arg132 of IDH1 was thought to be an early initiating event driving the evolution of gliomas." (PMID 36229714, 2023). "Missense mutations in IDH1/2 have been frequently observed in gliomas and acute myelogenous leukemia (AML), increasing the metastatic potential." (PMID 36672415, 2023). "IDH1/2 mutations are mostly found in low-grade gliomas and secondary GBMs that have a good prognosis for radiotherapy and alkylating agent chemotherapy." (PMID 37092846, 2023). "Gliomas stand alone as a type of cancer where the presence of the IDH1/2 mutation serves as a distinct and favorable prognostic indicator." (PMID 38201528, 2023).
glioma (continued). "Considering genetic criteria, gliomas can be divided into gliomas with IDH1/2 gene mutations and gliomas with IDH1/2 wild type genes." (PMID 37239035, 2023). "In 2016, the WHO revisited these guidelines recommending histopathological diagnosis in combination with molecular markers (e.g. IDH1/2 mutation status) to classify gliomas and other CNS tumors." (PMID 36991216, 2023). "G-CIMP and IDH1/2 mutant-codel subtypes are commonly observed in lower-grade gliomas and are associated with a favorable prognosis." (PMID 37749078, 2023). "An in vitro assay combining human TAMs with glioma cells for 24 h showed that the presence of IDH1 mutation within the glioma cells caused an increase in the expression of M1 genes and decreased that of the M2 genes." (PMID 37296846, 2023). "Lower-grade gliomas exhibit a high prevalence of isocitrate dehydrogenase 1 (IDH1) mutations, but faithful models for studying these tumors are lacking." (PMID 37149859, 2023). "In a recent study by Choate and colleagues in 2023, a promising technique for the rapid and extraction-free detection of the R132H isocitrate dehydrogenase 1 (IDH1) mutation in glioma samples was introduced." (PMID 38139688, 2023). "Eighty percent of low-grade gliomas have an IDH1 mutation, of which IDH1 R132H substitution is the most common." (PMID 36874119, 2023). "Additional assessment using patient-derived glioma cells with intrinsic IDH1 mutation would add more strength to our findings and is being pursued, but it is beyond the scope of this current report." (PMID 37218937, 2023). "We observed that either ectopic IDH1 mutant or its metabolite D2HG renders glioma cells susceptible to VSVΔ51 infection." (PMID 37880243, 2023). "In glioma, the presence of IDH1 mutation was associated with CpG hypermethylation of binding sites for the insulator protein CTCF (CCCTC-binding factor), disabling CTCF binding and correct establishment of DNA loops." (PMID 36411356, 2023). "This is consistent with previous reports of mutant IDH1 gliomas being associated with low levels of lactate dehydrogenase A." (PMID 37233647, 2023). "In recent years, the diagnosis of a subset of gliomas carrying the IDH1 R132H mutation (IDH1mt) has been made easy and reproducible due to the routine use of a mutation specific antibody." (PMID 37568909, 2023). "Patients with gliomas carrying mutations in either IDH1 or IDH2 enzymes have a relatively favorable survival, compared with patients with gliomas with wild-type IDH1/2 genes." (PMID 36959545, 2023). "Consequent pharmacological inhibition of the ATM pathway restored the tumor’s radiosensitivity, suggesting the translational potential to improve radiotherapy outcomes for patients with IDH1 gliomas harboring similar mutations." (PMID 37051530, 2023). "Due to its favorable PK properties, BAY1436032 has also been evaluated in clinical trials for the treatment of AML and various IDH1 mutated solid tumors, including gliomas, and showed a favorable safety profile but low overall response rates." (PMID 37049661, 2023). "In glioma, mutant IDH1 is deficient in performing its oxidative reaction by >80% with an approximate 38% reduction in NADPH generation, thus highlighting the metabolic consequences of mutation on its enzymatic and metabolic function." (PMID 37371524, 2023). "Eleven patients with high-grade gliomas harbored an oncogenic IDH1 mutation and were subsequently excluded from downstream analyses." (PMID 38143440, 2023). "In 2016 WHO categorization, codeletion of chromosomal arms 1p/19q (1p/19q codeletion) and isocitrate dehydrogenase 1 or 2 (IDH1 or IDH2) were included in the diagnostic typing for glioma classification." (PMID 36627482, 2023).
glioma (continued). "Although glioma xenografts carrying IDH1 mutations are very scarce, further investigation should be designed to compare the sensitivities of OVs in IDH1wt and IDH1mut xenografts." (PMID 37880243, 2023). "MEG3 expression was compared in patient‐derived glioma cells concerning IDH1 mutation and WHO grades." (PMID 37525401, 2023). "It is known that >90% of IDH1 mutant gliomas harbor an R132H mutation, with approximately 4% harboring an R132C mutation and the other subtypes occurring even less frequently." (PMID 37685329, 2023). "In this study, we have developed a CPNA-LAMP assay to specifically detect IDH1- R132H mutations rapidly in patient-derived glioma tumor lysates." (PMID 37733671, 2023). "We thus examined the expression of T cell and other genes by IDH1-mutated and IDH1-wild-type gliomas in The Cancer Genome Atlas (TCGA)." (PMID 37161052, 2023). "Knowledge of the IDH1 mutational status for a particular glioma can enable neurosurgeons to make informed decisions regarding the extent of resection." (PMID 37733671, 2023). "Total tumor resection, preoperative KPS score ≥60, IDH1/2 gene mutation, postoperative radiotherapy and chemotherapy were associated with better survival of patients with gliomas, while TERT promoter mutation was associated with poor survival (P<0.05)." (PMID 37250582, 2023). "Earlier studies have found a unique metabolic vulnerability in the sphingolipid pathway of gliomas with IDH1 mutations." (PMID 37198251, 2023). "At present, molecular pathological features (such as mutation status of isocitrate dehydrogenase gene IDH1 or IDH2) are used to classify adult glioma." (PMID 37698534, 2023). "IDH1 mutations work in tandem with other oncogenic events to promote astrocyte proliferation and glioma development." (PMID 37108511, 2023). "Cells derived from IDH1 mutated gliomas exhibit strong oxidative stress, evident by the increased expression of manganese superoxide dismutase." (PMID 37296846, 2023). "Mutations in IDH1 have been reported in more than 70% of low-grade gliomas and secondary glioblastomas." (PMID 35262263, 2023). "Five gliomas were shown to carry the IDH1 R132H mutation and the remaining three harbored wt IDH1, with the results being consistent with the IHC test results." (PMID 36810519, 2023). "Previous studies have demonstrated that genetic mutation that occur in cancer created the optimal cellular state for virus replication, which promotes us to investigate if IDH1 mutation in glioma confers sensitivity to oncolytic virus." (PMID 37880243, 2023). "Triptolide exhibited selective cytotoxicity in IDH1-mutated glioma cells both in vitro and in vivo, indicating a promising therapeutic alternative for IDH1-mutated malignancies." (PMID 37189700, 2023). "In gliomas, DNA methylation is tightly associated with mutations in genes coding for the IDH1/2 which results in glioma CpG island methylator phenotype (G-CIMP)." (PMID 36850002, 2023). "Specifically, 90% of patients diagnosed with IDH1-mutant oligodendroglioma present glioma-associated epilepsy." (PMID 38067243, 2023). "Loss of body weight was observed and >5% body weight loss occurred at DPI 15 for the mice bearing wild-type glioma tumor and IDH1 mutant glioma tumor." (PMID 37741882, 2023). "Glioma cells meeting the proneural signature most commonly had IDH1/2 mutations, as well as focal amplification of RTK receptor gene PDGFRA." (PMID 37345193, 2023). "Isocitrate dehydrogenase (IDH)-1 is frequently mutated in low-grade gliomas and secondary GBM, as well as in blood (AML) and liver tumors." (PMID 37161052, 2023). "The presence of IDH1 mutation correlates with a survival benefit and is more common among glioblastomas progressing from a lower grade glioma compared with 5–10% of de novo glioblastomas." (PMID 36900254, 2023). "IDH1/2 mutations are reported as a mutational cancer driver in several types of tumors, mostly in gliomas." (PMID 36941703, 2023).